IL6 (interleukin 6)
Diseases named in the same sentence as IL6 in open-access papers (continued):
Sharing a sentence is not in itself a finding about the gene and the disease.
urticaria (22 papers, 2013 to 2026). A vascular reaction of the skin characterized by erythema and wheal formation due to localized increase of vascular permeability. "According to a handful of studies, a significant association between serum IL-6 levels and urticaria activity was found (measured by the Urticaria Activity Questionnaire, or UAS7), as well as between IL-6 and impaired quality of life as measured by the DLQI." (PMID 37626727, 2023). "It was found that urticaria was associated with higher concentrations of IL-6 and IL-17A and lower values of IL-18, IL-23, RANTES and IP-10." (PMID 36539847, 2022). "ROC analysis showed that IL-6 has high sensitivity and specificity as a parameter associated with the acute phase of urticaria." (PMID 36539847, 2022). "A significant association between IL-6 and IP-10 with the acute phase of urticaria has been demonstrated." (PMID 36539847, 2022). "One mechanism comprehends the involvement of IL-6, which increases endothelial permeability in an in vitro study and has been linked to urticaria flares: it increases in patients with ongoing urticaria and reduces when urticaria symptoms go into remission." (PMID 36830946, 2023). "Molecular hypothesis reflects the co-relation of IL-6 that is associated with SARS-CoV-2 infection with the pathogenesis of urticaria." (PMID 36146777, 2022). "Mycoplasma pneumoniae can provoke urticaria through immune complex deposition, IgE overproduction, or proinflammatory cytokine release (e.g., IL-6, IL-8)." (PMID 41562994, 2025). "In vitro experiments have shown that IL6 increases endothelial permeability, a key mechanism in the pathogenesis of urticaria." (PMID 35181847, 2022). "Among the cytokines and chemokines studied, IL-6 and IP-10 seem to be useful in differentiating children with acute phase of urticaria and healthy ones." (PMID 36539847, 2022). "IL-6 and IP-10 seem to be useful in differentiating children with acute phase of urticaria and healthy ones." (PMID 36539847, 2022). "To elucidate the effects of PF on the inflammatory cytokine release in urticaria, we measured the mRNA levels of IL-12, IL-6, IFN-γ, and IL-4 in skin lesions using qRT-PCR." (PMID 35222003, 2021). "As such the clinical presentation of urticaria can aid diagnostic assessment, while considering risk factors, such as G6PD deficiency and aberrant IL‐6 expression." (PMID 32986289, 2021). "Since now there is no study in the literature describing the levels of all four ILs (IL-4, IL-6, IL-8 and IL-10) in the patients with urticaria." (PMID 24578755, 2014). "Our study concerns four ILs, IL-4, IL-6, IL-8 and IL-10, simultaneously and their quantitative changes during the acute phase of urticaria as well as 2 weeks after drug administration." (PMID 24578755, 2014). "Our previous findings showed the importance of analysing the peripheral markers of acute phase response (APR) activation, C-reactive protein (CRP) and IL-6 in the context of urticaria activity and severity." (PMID 23207551, 2013). "S100A7, S100A8, S100A9, S100A12, IL6 and SOCS3, whose mRNA expression correlated positively with the urticaria activity score and may have a potential diagnostic value." (PMID 40635160, 2025). "IL-6 serum levels have also been studied in patients with urticaria." (PMID 24578755, 2014). "Microarray analyses have identified IL-6, TNF-α, NF-κB, and TLR-4 as pivotal genes in urticaria pathogenesis." (PMID 40490797, 2025). "Two years later (2019), Puxeddu and colleagues continued their exploration of the clinical implications of biomarkers in urticaria, introducing additional potential indicators such as ESR and white blood count (WBC), and serum level of IL-6." (PMID 38671667, 2024). "IL-6 is an acute phase protein closely related to the production of CRP and fibrinogen, whose levels are elevated during urticaria exacerbations." (PMID 36539847, 2022).
urticaria (continued). "Serum concentrations of C-reactive protein (CRP) and interleukin 6 (IL-6), key markers of acute phase response and of D-dimer, a marker of fibrin turnover were investigated in 58 CSU patients assessed with the urticaria activity score (UAS) and the controls." (PMID 30026764, 2018). "In contrast, high disease activity, inducible urticaria, elevated CRP or IL-6 levels, and hematological features such as increased neutrophil-to-lymphocyte ratio, basopenia, eosinopenia, and markers of coagulation activation (e.g., D-dimer, fibrinogen) are linked to resistance." (PMID 41602870, 2026). "Since urticaria activity often changes, overall disease activity is best measured by the daily UAS and serum IL-6 (a better indicator of short-term snapshots of disease severity (once-daily UAS)), and disease impact on quality of life, by the DLQI, as supported by our study." (PMID 37626727, 2023). "There have been studies evaluating the levels of isolated ILs in patients with urticaria, but none of them compared the levels of the four ILs in the same patient (IL-4, IL-6, IL-8 and IL-10)." (PMID 24578755, 2014). "Although our pilot study found a correlation between IL-6 and the once-daily UAS, IL-6 was not significantly connected to the UAS7 and UCT, probably due to the small number of participants enrolled and due to frequent changes in urticaria activity." (PMID 37626727, 2023).
abscess (21 papers, 2010 to 2026). An inflammatory process characterized by the accumulation of pus within a newly formed tissue cavity which is the result of a bacterial, fungal, or parasitic infection or the presence of a foreign body. "Collectively, however, our findings indicate that mleS contributes to abscess formation in mouse skin, which is associated with reductions in the production of IL-6 and lactic acid, the underlying mechanisms of which await further investigation." (PMID 37052483, 2023). "Although the mechanisms whereby mleS contributes to abscess formation remain to be elucidated, our observations lead us to believe that these are probably associated with the production of IL-6 and lactic acid, which facilitate inflammatory metabolic adaptation." (PMID 37052483, 2023). "In this regard, our findings revealed that the loss of mleS hampered abscess formation in mouse skin when assessed on the first and third days of infection, which is consistent with our observations of increases in the production of the inflammatory cytokine IL-6 in wild-type BS19." (PMID 37052483, 2023). "Inflammation reaction has been identified in PPV as the formation of abscesses by neutrophil and eosinophil and the presence of Interleukin-6 (IL-6), Interleukin-8 (IL-8), and Tumor Necrosis Factor-alpha (TNF-α)." (PMID 40565944, 2025). "On day 56, after stimulation with Poly I:C, IL-6 was increased in Zn150 non-abscess compared to Zn150 abscess (TRT × abscess P = 0.04), all other treatments were not different." (PMID 38764468, 2024). "A low concentration of Il6 facilitates the development of abscesses in the liver, while a low expression of Serpinb9c increases the sensitivity of hepatocytes to death by natural killer cells." (PMID 39591294, 2024). "Sinuses and abscesses, located in the anterior sites, are more frequent than nodules; furthermore, elevated serum levels of IL-1, C-reactive protein, IL-17 and IL-6 were found." (PMID 37484864, 2023). "These reductions in abscess size were found to be correlated with lower levels of proinflammatory cytokines, such as IL-6." (PMID 37052483, 2023). "The expression of lncRNA NEAT1 was related to segments of the lesions, paraspinal abscesses, anti-TB treatment, drug resistance, interleukin-6 (IL-6), C-reactive protein (CRP), and erythrocyte sedimentation rate (ESR)." (PMID 35465262, 2022). "Unfortunately, IL-6 inhibition leads to severe side effects, like the development of abscesses or perforation, as demonstrated with the IL-6 inhibitor PF-04236921." (PMID 33435303, 2021). "The treatment of these mice with an anti-IL-6 antibody led to a reduction of neutrophil micro-abscesses in the skin, showing the importance of IL-6 in the context of myelomonocytic cells." (PMID 26999594, 2016). "In previous studies, we found paradoxically altered IL-6 levels in Crh−/− mice following turpentine-induced abscess formation, although to the opposite direction of the one found in the fibroblasts." (PMID 21765902, 2011). "However, there were several interactions between dietary Zn treatment and abscess presence for IL-6 and IL-1β production." (PMID 38764468, 2024). "Decreased IL-6 secretions by polymorphisms in TLR genes could result in a weakened immune response to infection, and thus in less abscess formation." (PMID 31786695, 2020). "Furthermore, anti-IL-6 therapy in IBD patients ameliorated the disease, but increased the risk of developing GI abscesses and perforation, suggesting that IL-6 contribute to inflammatory processes, but also may maintain epithelial barrier." (PMID 34124086, 2021). "In vivo, pixantrone (30 mg/kg) decreased serum CRP, IL-6, and TNF-α levels while diminishing abscess sizes and splenic bacterial loads (P < 0.05 vs. untreated)." (PMID 41294339, 2026). "In murine models, PIX (30 mg/kg i.v.)reduced inflammatory markers (CRP, IL-6, TNF-α), abscess size, and bacterial loads to levels comparable with ΔhisD infection." (PMID 41294339, 2026).
abscess (continued). "On day 13, there was a TRT × abscess effect (P ≤ 0.03) after stimulation with PAM3CSK for both IL-6 and IL-." (PMID 38764468, 2024). "IL-6 and TNF-α were significantly higher in patients in the abscess group compared with the control group (p < 0.01)." (PMID 37091905, 2023). "However, co-administration of α-MG-4 and penicillin resulted in a drastic reduction in abscess size, accompanied by a significant decrease in CFU number and concentration of IL-6 (P ≤ 0.01–0.001)." (PMID 39508612, 2024). "In addition, IL-6 and TNF-α were significantly decreased in patients in the surgical group compared with the abscess group (p < 0.01)." (PMID 37091905, 2023). "In the absence of IL-6, the abscess formation is inhibited, which suggests that the recruitment, activation, and survival of CD4 T cells are required for the induction of abscess formations." (PMID 21234388, 2010). "Previously, we demonstrated that auranofin applied topically is effective in significantly reducing the burden of MRSA in an uncomplicated abscess model in mice and in decreasing expression of pro-inflammatory cytokines (TNF-α, MCP-1, IL-1β, and IL-6) that may impair wound healing." (PMID 32350417, 2020). "For IL-6, Zn150 non-abscessed was increased compared to CON abscess and Zn100 non-abscess, Zn100 abscess was also increased compared to CON abscess." (PMID 38764468, 2024). "On day 13, after stimulation with PAM3CSK, Zn150 steers without abscesses had the greatest cytokine (IL-6 and IL-1β) production, and were higher than CON abscessed steers and Zn100 steers without abscesses." (PMID 38764468, 2024).
chronic gastritis (21 papers, 2012 to 2025). Inflammation of the stomach that is chronic in nature. "H. pylori infection causes chronic gastritis and induces an inflammatory response that increases the pro-inflammatory factors interleukins (IL-1β, IL-6, IL-8, IL-17), tumour necrosis factor α (TNF-α), interferon γ (IFN-γ), and C-reactive protein (CRP)." (PMID 38475712, 2024). "BAFF promotes elevated inflammatory factors such as IL-1β, IL-6, IL-23, and TGF-β in Helicobacter pylori-associated chronic gastritis." (PMID 35320937, 2022). "Recently, IL-6 is reported to play an important role in the treatment of chronic gastritis in Zuojinwan." (PMID 34471638, 2021). "BAFF promotes the production of several inflammatory mediators in Hp-related chronic gastritis, including IL-1β, IL-6, IL-23, and TGF-β." (PMID 33324396, 2020). "A potential mechanism by which H. pylori induces IL-6 production by macrophages in chronic gastritis patients was reported to be related to heat shock protein 60 stimulation." (PMID 31065302, 2019). "In the Hp+ chronic gastritis before treatment group, IL6 mRNA expression was negatively correlated with the expression of miR‐103 (r = −0.82; p < 0.001) and miR‐370 (r = −0.52; p = 0.048)." (PMID 26945693, 2016). "A pronounced IL-6 level at later stages might indicate ongoing inflammation in the gastric lining with potentially developing chronic gastritis." (PMID 38602383, 2025). "First, H. pylori infection may result in chronic gastritis and induce systemic inflammation with the release of cytokines, including tumor necrosis factor- 훼, interleukin-1 and interleukin-6." (PMID 29699505, 2018). "H. pylori infection causes chronic gastritis and induces a permanent inflammatory response that may increase both the gastric and the systemic indexes of inflammation, such as TNF-α, IL-1, and IL-6." (PMID 29743888, 2018). "Notably, levels of IL-1α, IL-1β, IL-6, and IL-12, which are the main contributors to human chronic gastritis, were decreased in Nrdc−/− mice." (PMID 28230087, 2017). "It has been shown that the level of the pro-inflammatory cytokines IL1β, IL6, IL8, and TNFα were positively correlated with the level of chronic gastritis but that correlation disappear in the presence of gastric atrophy and was inverse, for IL6 and IL8, in intestinal metaplasia." (PMID 23248648, 2012). "H. pylori infection results in increased expression of TNFA, IL6, IL12A and IL2 in the gastric mucosa, in addition to the effect of chronic gastritis, and for TNF‐α and IL‐2 proteins, this increase was mainly observed in inflammatory cells." (PMID 26945693, 2016). "IL-8 leads to the migration of neutrophils and monocytes into the mucosa; the activated monocytes and dendritic cells stimulate the production of various cytokines, such as IL-4, IL-5, IL-6 and interferon-γ (IFN-γ), leading to an inflammatory reaction (chronic gastritis)." (PMID 32403331, 2020). "In addition, increased production of IL-6 and TNF-α in human antral mucosa cultures from H. pylori-infected chronic gastritis patients has been observed by others." (PMID 31065302, 2019). "Herein, we assessed whether H. pylori infection and its eradication, beyond its cagA virulence genotype, change the expression of inflammatory mediators (TNFA, IL6, IL1B, IL12A, IL2 and TGFBRII) in chronic gastritis patients." (PMID 26945693, 2016). "mRNA and protein expression of TNFA, IL6, IL1B, IL12A, IL2 and TGFBRII and miRNAs miR‐103a‐3p, miR‐181c‐5p, miR‐370‐3p, miR‐375 and miR‐223‐3p were evaluated in tissue samples from 20 patients with chronic gastritis H. pylori negative (Hp−) and 31 H." (PMID 26945693, 2016).
chronic lymphocytic leukemia (21 papers, 1997 to 2025). "Interleukin-6 (IL-6) is involved in inflammation and has a significant role in chronic lymphocytic leukemia (CLL) progression." (PMID 38024543, 2023). "Autocrine secretion-activated interleukin-6 (IL-6) in chronic lymphocytic leukemia (CLL) cells upregulates miR-19a, which disrupts toll-like receptor-7 (TLR-7) signaling." (PMID 29050336, 2017). "Exosomal transfer from chronic lymphocytic leukemia (CLL) cells to monocytes enhanced the secretion of cytokines, including CCL2, CCL4, and IL-6, while upregulating PD-L1 expression." (PMID 41502528, 2025). "Transcriptomic profiling from chronic lymphocytic leukemia patients successfully treated with CAR-T cells, revealed a general implementation of the IL-6/STAT3 signaling pathways, as indicated by increased production of IL-6, IL-17, IL-22, IL-31 and CCL20." (PMID 30999624, 2019). "In chronic lymphocytic leukaemia (CLL) highly functional CAR T cells were enriched in memory-related genes including STAT3 and IL-6 signatures, while non-responders had upregulated genes associated with effector differentiation, glycolysis, exhaustion and apoptosis." (PMID 31970440, 2020).
kidney injury (21 papers, 2015 to 2026). Trauma to the kidney. "Interleukin-6, encoded by IL6, is a pleiotropic cytokine and was found to contribute to acute and chronic kidney injury and fibrosis." (PMID 35327386, 2022). "In conclusion, this study highlights the role of meprin β activity in regulating cellular proliferation through PCNA regulation, driven by the IL-6-mediated AKT/ERK signaling pathway during the recovery phase following IR-induced kidney injury." (PMID 39975921, 2025). "We previously showed that meprin β modulates cellular survival (BCL-2) through IL-6/JAK/STAT signaling pathway in IR-induced kidney injury." (PMID 39975921, 2025). "While our results suggest that meprin β regulates cellular proliferation through the IL-6-mediated AKT/ERK signaling pathway during the repair phase of IR-induced kidney injury, further studies are needed to elucidate this interplay and its role in recovery." (PMID 39975921, 2025). "The goal of the current study was to determine how meprin β modulation of the IL-6 signaling pathway impacts downstream cellular proliferation in IR-induced kidney injury." (PMID 39975921, 2025). "The data provide evidence for meprin β modulation of IL‐6/JAK2/STAT3 signaling and their convergence to activate the downstream target genes of IL‐6 signaling in IR‐induced kidney injury." (PMID 36117389, 2022). "IL-6 is a known mediator of nephrotoxic injury and its absence prevents HgCl2 induced kidney injury." (PMID 26990086, 2016). "In conclusion, the study demonstrated that EA at BL23 exhibited anti‐HUA and nephroprotective effects by inhibiting both the NLRP3 inflammasome and the IL‐6/JAK/STAT3 signaling pathway, reducing renal inflammation and supporting its therapeutic potential for HUA‐associated kidney injury." (PMID 41278550, 2025). "Hyperoxia-induced kidney injuries are influenced by several molecular factors, including hypoxia-inducible factor-1α and interleukin-6/Smad2/transforming growth factor-β, and Wnt/β-catenin signaling pathways; these are key to cell proliferation, tissue inflammation, and cell membrane repair." (PMID 35955627, 2022). "In particular, TNF-α, IL-1β, and IL-6 play a key role in cisplatin-induced kidney injury." (PMID 32089779, 2020). "Propofol has been demonstrated to inhibit TNF-α, IL-6, and CXCL-10 expression in I/R-induced kidney injury." (PMID 39054453, 2024). "Since S100A8/A9 can activate different receptors, such as TLR4, to promote leukocyte recruitment and secretion of proinflammatory cytokines, such as IL-6 and TNF-α, leading to kidney injury." (PMID 37547329, 2023). "The goal of this study was to determine how meprin β expression impacts IL‐6 and downstream modulators of the JAK2‐STAT3‐mediated signaling pathway in IR‐induced kidney injury." (PMID 36117389, 2022). "Therefore, the goal of the current study was to determine how meprin β activity impact IL-6 mediated ERK/AKT pathway and downstream cellular proliferation in IR-induced kidney injury." (PMID 39975921, 2025). "Semaglutide could act as a protective agent against acute kidney injury by reducing inflammatory molecules such as tumor necrosis factor-alpha (TNF-α) and its cognate receptor, TNF-α R, interleukine-6 (IL-6)." (PMID 36937464, 2023). "In summary, our data suggest that proteolytic processing of IL‐6 by meprin β plays an important role in modulating IL‐6 expression and influences the downstream signal transduction/pathway mediated via JAK2/STAT3 in IR‐induced kidney injury." (PMID 36117389, 2022). "The underlying mechanism study showed that NF-κB activation triggers the release of inflammatory cytokines such as interleukin-1beta (IL-1β), interleukin-6 (IL-6) and tumor necrosis factor alpha (TNF-α) that exacerbating kidney injury (Place and Kanneganti., 2018)." (PMID 36278223, 2022).